CTLA4 (cytotoxic T-lymphocyte associated protein 4)
Diseases named in the same sentence as CTLA4 in open-access papers (continued):
Sharing a sentence is not in itself a finding about the gene and the disease.
melanoma (continued). "The introduction of monoclonal antibodies targeting cytotoxic T lymphocyte antigen-4 (CTLA-4), program death protein 1 (PD-1), or lymphocyte activation gene-3 (LAG-3) dramatically changed the prognosis of patients with late-stage melanoma." (PMID 40507314, 2025). "Another anti-CTLA4 antibody is Ipilimumab, the first ICI approved by the FDA in 2011 for advanced melanoma." (PMID 40584631, 2025). "While surgical excision remains the primary treatment method, systemic treatments such as PD-1 and CTLA-4 inhibitors, BRAF/MEK-targeted agents, and, in some cases, chemotherapy or radiation therapy play a crucial role in managing malignant melanoma." (PMID 40282947, 2025). "Adding anti-CTLA4 to the combinations identified in the CRC model was necessary to achieve a complete response in breast and melanoma MMRd cancer models, which is consistent with other studies." (PMID 40027748, 2025). "JQ1 combined with checkpoint blockade (anti-PD-1 or anti-CTLA-4) improved CD8+/Treg ratios and Th1 activation in melanoma and lung adenocarcinoma models, and similarly enhanced anti-tumor T cell responses in prostate cancer models." (PMID 41583469, 2025). "Using anti-LAG3 or anti CTLA4 with anti-PD-1 is promising for MMRd CRC patients 41,42 and other cancers such as melanoma 43,44." (PMID 40027748, 2025). "This strategy represents a novel approach to inducing host responses against tumors, as evidenced by the survival rate increase observed in melanoma patients and lung cancer patients treated with a combination of PD1 and CTLA-4 inhibition." (PMID 39329742, 2024). "Checkpoint inhibitors like ipilimumab, a CTLA-4 antibody, and PD-1 inhibitors have shown significant improvements in response rates, PFS, and OS in advanced melanoma." (PMID 39682109, 2024). "Recently, there have been significant advancements in therapies for treating stage III and IV melanomas, including targeting molecular pathways using BRAF and MEK inhibitors or immune checkpoint inhibitors, such as PD-1, CTLA-4, or LAG-3 inhibitors." (PMID 38927967, 2024). "Research shows that cytotoxic T-lymphocyte antigen-4 (CTLA-4) inhibitors, the first ICI approved by the U.S. Food and Drug Administration (FDA), can improve survival rates in patients with advanced melanoma." (PMID 39896816, 2024). "Clinical studies focusing on melanoma, RCC, squamous cell carcinoma, and NSCLC have shown remarkable increases in patient survival with both CTLA-4 and PD-1 checkpoint inhibitors compared to conventional chemotherapy." (PMID 38375475, 2024). "Ipilimumab, a CTLA-4 inhibitor, was approved by the U.S. Food and Drug Administration (FDA) on March 25, 2011, for the treatment of unresectable advanced melanoma." (PMID 38294629, 2024). "Tremelimumab is the other approved CTLA-4 antibody, and its Grade ≥ 3 TEAE rate reported in the phase 3 trial with advanced melanoma was 52%." (PMID 39354625, 2024). "The efficacy of ICI therapies, including the anti-CTLA4 (ipilimumab) and anti-PD-1 (nivolumab and pembrolizumab) monoclonal antibodies, is well established in patients with stage III/IV melanoma." (PMID 38673829, 2024). "In melanoma cell lines B16-F0 and B16-F1, approximately 30-40% of CSCs expressed CTLA-4, and blockade of CTLA-4 suppressed stem cell-like properties and significantly inhibited spheroid formation in vitro." (PMID 39611156, 2024). "Combination of anti-CTLA4 and anti-PD1 antibodies were effective in melanoma, renal cell carcinoma, and microsatellite instability-high (MSI-H) colorectal cancers, and concomitant blockade of CTLA4 and PD1 increased production of IFNγ from CD8+ cells." (PMID 39095793, 2024). "This significant increase in response rates and median survival times has been observed in melanoma and RCC, leading to the approval of the ipilimumab (anti-CTLA-4 mAb) and nivolumab (anti-PD-1 mAb) combination for the treatment of these cancers." (PMID 38375475, 2024).
melanoma (continued). "Together, mutational frequencies were similar between metastases progressing or relapsing on either anti-CTLA4 or anti-PD1 and ICB naïve melanomas." (PMID 38594286, 2024). "Ipilimumab, a CTLA-4 inhibitor, was the first ICI to be approved by the FDA in 2011, for use in melanoma." (PMID 38345654, 2024). "Data from small cohorts of melanoma patients treated with ICIs suggest that the integrity of the IFN-γ pathway is essential for the responsiveness to anti-PD1 and anti-CTLA-4 treatment." (PMID 39195270, 2024). "Ipilimumab is a humanized IgG1 monoclonal antibody that binds to CTLA-4 in the B7 interaction domain, mediating steric hindration to block the binding of CTLA-4 to B7, and is the first CTLA-4 antibody drug used in advanced melanoma." (PMID 38177102, 2024). "Taken together, these in vivo studies demonstrated that the combination of ICIs (a-PDL1 and a-CTLA4) with LDHIs (Oxa and NHI-2) enhances the efficacy of ICIs in a melanoma tumor model." (PMID 39435293, 2024). "A study employed the combination of CTLA-4 inhibitor (KD6001) and tori for advanced melanoma patients, including 9 (31.0%) of AM." (PMID 39572525, 2024). "Patients previously treated with the anti-PD-1 and anti-CTLA-4 combination and those with BRAF wild-type melanoma seemed to benefit more from this second-line strategy." (PMID 38956747, 2024). "Based on the successful results of a randomized clinical trial, the anti-CTLA-4 monoclonal antibody ipilimumab became the first ICI approved for cancer treatment and was used in the setting of advanced melanoma." (PMID 38673058, 2024). "In 2011, ipilimumab (anti-CTLA-4) was approved by the US Food and Drug Administration (FDA) to be the first checkpoint inhibitor applicable for melanoma treatment." (PMID 38673829, 2024). "Treatment with immune checkpoint inhibitors, such as anti-PD1, anti-PD-L1, anti-CTLA-4, and anti-LAG3, in the setting of late-stage melanoma has significantly improved the long-term survival of patients vs. previous standard-of-care therapies." (PMID 38312842, 2024). "In both the Y1.7LI melanoma model and MC38 model, NeoAg vaccines combined with either anti-CTLA-4 or anti-PD-1 leads to equal or even better anti-tumor immune responses than even combination anti-CTLA-4 and anti-PD-1." (PMID 38187708, 2024). "Distinct from ipilimumab (Yervoy), an FDA-approved melanoma treatment that blocks CTLA-4 to stimulate the immune response, abatacept mimics CTLA-4 on T cells." (PMID 38807592, 2024). "Neoadjuvant immunotherapies with CTLA-4 and PD-1 have demonstrated significant pathological responses with a relapse-free survival among approximately 80% of patients with stage III melanoma." (PMID 38399429, 2024). "We utilized two immunotherapy-related datasets: the uroepithelial carcinoma dataset (IMvigor210), comprising samples treated with anti-PD-1, and the malignant melanoma dataset (GSE91016), involving samples treated with both anti-PD-1 and anti-CTLA-4." (PMID 38570787, 2024). "Immune checkpoint inhibitors, which target inhibitory pathways such as PD-1/PD-L1 and CTLA-4, have revolutionized the treatment of several solid tumors, including NSCLC, melanoma, renal cell carcinoma, and more." (PMID 39518676, 2024). "Clinical trials are currently in progress to investigate the effectiveness of anti-CTLA-4 and IDO-inhibiting therapy in melanoma patients." (PMID 39534873, 2024). "PD-1/PD-L1 and CTLA-4 inhibitors have been approved by the FDA and have achieved favorable efficacy in non-small cell lung cancer (NSCLC), melanoma and renal cell carcinoma (RCC)." (PMID 39249163, 2024). "Over the past several decades, advancements in the treatment of BRAF-mutant melanoma have led to the development of BRAF inhibitors, BRAF/MEK inhibitor combinations, anti-PD-1 therapy, and anti-CTLA4 therapy." (PMID 39336897, 2024). "Melanoma is the cancer most frequently treated with monoclonal antibodies against PD-1 (anti-PD-1), CTLA4 (anti-CTLA-4) and PD-L1 (anti-PD-Ll)." (PMID 38007054, 2024).
melanoma (continued). "In the last few years, the use of checkpoint inhibitors such as ipilimumab (anti-CTLA4), pembrolizumab (anti-PD1), and nivolumab (anti-PD1) has improved the treatment of certain tumors, like melanoma and non-small-cell lung carcinoma." (PMID 39272823, 2024). "An in silico analysis identified key molecular players, including IL-6 and CTLA4, in the HCV-melanoma network." (PMID 39336572, 2024). "The research progress on immune checkpoint inhibitors is rapid, especially monoclonal antibodies targeting PD-1/PD-L1 and CTLA-4, which have been approved by the FDA for first-line treatment of melanoma and/or lung cancer." (PMID 39555054, 2024). "For melanoma, it has been shown that patients with low copy number burden benefit more from either single agent anti-CTLA-4 or anti-PD-1, or anti-CTLA-4 followed by anti-PD-119,41,53–55." (PMID 39428388, 2024). "The data indicate that autologous DCs, pulsed with the melanoma antigen recognized by T cell 1 (MART-1) peptide, were administered alongside escalating doses of Tremelimumab (an anti-CTLA-4 antibody) to 16 patients with advanced melanoma." (PMID 39062753, 2024). "In summary, the observations indicate a sustained immune response in some tumors despite progressing on anti-CTLA4; in contrast, a particularly immune-poor microenvironment was observed in anti-PD1 resistant melanoma." (PMID 38594286, 2024). "Using an orthotopic model of melanoma, we observed that CXCR3KO mice displayed low responsiveness to anti-PD-1 and anti-CTLA-4 immunotherapy." (PMID 39474427, 2024). "The net outcome culminates in impaired T-cell lymphoma, breast cancer and melanoma growth in vivo especially when combined with anti-CD47, anti-CTLA-4 or anti-PD-1 depending on the animal model." (PMID 38831284, 2024). "Ipilimumab, a CTLA-4 blocker, is the first FDA-approved drug targeting an immune checkpoint to treat melanoma." (PMID 38791528, 2024). "Over the past several decades, multiple treatment approaches to managing BRAF-mutant melanoma have been developed, including BRAF inhibitors, BRAF/MEK inhibitor combinations, anti-PD-1 therapy, and anti-CTLA4 therapy." (PMID 39336897, 2024). "We examined the in vivo antitumor efficacy of the anti-CTLA-4 VHH (H11)-VHHkappa conjugate in the MC38 mouse colon carcinoma and B16-F10 melanoma models." (PMID 39149504, 2024). "DR-18 in combination with anti–CTLA-4 demonstrates enhanced in vivo activity in RCC and melanoma murine models." (PMID 39561007, 2024). "In a study conducted by Coutzac and colleagues in both mice and melanoma patients treated with anti-CTLA-4 monoclonal antibody, the authors found that SCFAs limited the efficacy of anti-CTLA-4 treatment." (PMID 36911704, 2023). "CTLA-4 blocking mAbs are approved for the treatment of HCC, NSCLC, melanoma, renal cell carcinoma, mesothelioma, CRC, and cutaneous squamous cell carcinoma." (PMID 37446039, 2023). "Nevertheless, it was also reported that blockage of TNF overcome the resistance to anti-PD-1 treatment in experimental melanoma, and the treatment with TNF inhibitors enhanced the anti-tumor effect of combined CTLA-4 and PD-1 immunotherapy." (PMID 36865537, 2023). "Ruminococcaceae species were also common in melanoma patients (n = 38, stage III) gut samples among responders to neoadjuvant anti-PD1 and anti-CTLA4 combination." (PMID 36737654, 2023). "A cohort of patients with stage IIIC/IV melanoma was analyzed to examine the relationship between STAT1 post-translational modifications and RFS in response to anti-CTLA-4 adjuvant therapy." (PMID 36980641, 2023). "Envisioning this as an important anti-cancer tool, the first immune checkpoint inhibitor (ipilimumab) was developed against CTLA-4 in 1996 and subsequently approved by the FDA in 2011 for treatment in advanced melanoma." (PMID 38275827, 2023).
melanoma (continued). "In melanoma patients treated with anti-PD-1 antibodies, peripheral CD8+ T cells were proliferative and showed co-expression of PD-1 and CTLA-4 at day 7 after treatment, but only in responsive patients." (PMID 37881432, 2023). "Some miRNAs can regulate the expression of immune checkpoint molecules such as PD-L1, CTLA-4, and TIM-3, thereby influencing the immune response against melanoma cells." (PMID 37504268, 2023). "In contrast, in melanoma patients from the Nathanson_2017 cohort, it was observed that patients with low expression of SLC1A5 who received ai_CTLA-4 treatment had a worse prognosis." (PMID 37566748, 2023). "Mice bearing flank tumors (B78 melanoma or A20 lymphoma) were treated with combinations of CpG, OX40, and anti-CTLA-4." (PMID 37016127, 2023). "Twenty-six patients with advanced melanoma underwent isolated limb infusion (ILI), a treatment similar to ILP, and were then given systemic treatment with CTLA4 inhibition." (PMID 36672422, 2023). "Otherwise, the response of melanoma patients to immunotherapy induces resistance to anti-PD1 and anti-CTLA-4 treatment." (PMID 37662962, 2023). "We first investigated the association between the pre-treatment APM gene expression patterns and patient survival in two melanoma cohorts receiving anti-PD1 (n = 122) and anti-CTLA4 (n = 40) treatment." (PMID 36653470, 2023). "Melanoma patients who responded to adoptive T-cell therapy (ACT) treatment (GSE35640), anti-PD-1 (PUCH, Gide19, and Liu19 cohorts) or anti-CTLA-4 (VanAllen15 cohort) showed a significant lower ICDscore than those who were non-responders to immunotherapies." (PMID 37036471, 2023). "Published studies have explored the combination of single or dual CTLA4/PD-1 inhibitors and MYB oncoprotein targeting DNA vaccines, SSX2 cancer antigen, PSMA prostate-specific antigen, and TRP-2 and gp100 melanoma-specific antigens." (PMID 37138873, 2023). "Anti-PD-1/PD-L1 and anti-PD-1/CTLA-4 therapy had minimal impact on the richness, diversity, and species abundance of the intestinal microbiome of patients with advanced NSCLC, RCC, and melanoma, when comparing baseline and week 12 of treatment." (PMID 37444378, 2023). "One study treated murine melanoma tumor models with a CSC-dendritic cell vaccine, combined with PD-L1 and CTLA-4, and the triple combination treatment significantly enhanced the eradication of CSCs." (PMID 37251931, 2023). "In recent years, immune checkpoint blocking using anti-CTLA-4 and anti-PD-1 antibodies has been successfully applied to tackle some types of advanced tumors, including non-small cell lung cancer (NSCLC), melanoma, bladder cancer, and Hodgkin’s lymphoma." (PMID 37059586, 2023). "Other changes observed in melanoma-bearing sentinel LN include (i) reduced CD69+CD8+T cell/Treg cell ratio, (ii) high PD-1 expression on CD4+T and CD8+T cells, and (iii) high CTLA-4 expression on γδ T cells." (PMID 38065972, 2023). "As CTLA-4 is an immune checkpoint that negatively regulates T-cell activation, we aim to investigate the significance of lower CTLA-4 expression in melanoma patients." (PMID 37197667, 2023). "TIL therapy was initially developed to treat melanoma patients, and has shown to improve PFS compared to anti-CTLA-4 in patients refractory to anti-PD1." (PMID 37079257, 2023). "In the VanAllen 2015 cohort of melanoma tumors, patients with high USP28 expression responded 10% to anti-CTLA4 therapy, which was significantly lower than the 36.3% response rate observed in low-USP28 expression patients." (PMID 37450415, 2023). "A high level of C3 expression suggested a good outcome for immune checkpoint blockade (ICB) therapy targeting PD1, CTLA4, and ACT in melanoma, but a bad outcome for ICB therapy targeting PD1 and PDL1 in GBM and bladder cancer." (PMID 37907575, 2023). "Combining CTLA-4 and PD-1 ICI enhanced the therapeutic effect compared with either therapy alone in melanoma patients." (PMID 36831435, 2023).
melanoma (continued). "For instance, ipilimumab, a human monoclonal antibody that blocks CTLA-4, was reported to significantly improve the OS, distant metastasis-free survival, and recurrence-free survival for stage III melanoma." (PMID 37205993, 2023). "The establishment of an immunosuppressive microenvironment is also mediated by the upregulation of the inhibitory immune checkpoints (PD-L1/PD-1, CTLA-4, TIGIT, LAG-3) by melanoma cells or those of the surrounding microenvironment." (PMID 36768978, 2023). "Immune checkpoint inhibitors, specifically anti-CTLA4, anti-PD1, and anti-PDL-1 antibodies, are commonly used to treat skin cancers, including melanoma, SCC, BCC, and Merkel cell carcinoma." (PMID 38067165, 2023). "The first drug for the treatment of melanoma to receive FDA approval was ipilimumab, a CTLA-4 inhibitor." (PMID 37038154, 2023). "FDA-approved monoclonal (mAb) anti-CTLA4 and anti-PD-1 antibodies as ICI have been successful in the management of advanced melanoma." (PMID 36834917, 2023). "Clinical management of melanoma LMD consists primarily of radiation therapy, BRAF/MEK inhibitors as targeted therapy, and immunotherapy with anti-PD-1, anti-CTLA-4, and anti-LAG-3 immune checkpoint inhibitors." (PMID 36980770, 2023). "Another important immune regulatory cell in melanoma and other cancers is Treg cells (CD4+CD25+ regulatory T cells), which have an immunosuppressive function by increased expression of CTLA-4 and PD-1, resulting in suppression of antitumor immunity." (PMID 37037839, 2023). "In this study, we collected a total of 631 melanoma and 109 non-small cell lung cancer (NSCLC) samples treated with ICI agents (i.e., anti-CTLA-4, anti-PD-1/PD-L1, or combination therapy)." (PMID 37535001, 2023). "In 2011, the FDA accepted the anti-CTLA4 immuno- and BRAF inhibitory targeted therapeutic modalities, which at last resulted in a breakthrough for the treatment of melanoma patients with poor expected outcomes." (PMID 37568785, 2023). "Liver X receptor agonists have been combined with other antitumor agents with promising activity in preclinical studies of melanoma (vemurafenib, dacarbazine [DTIC], anti‐CTLA‐4 antibody) and pancreatic cancer (gemcitabine)." (PMID 37341140, 2023). "In the context of melanoma treatment, the inhibitory signals between antigen-presenting cells and T cells controlled by the CTLA-4 molecule can be blocked by anti-CTLA-4." (PMID 37666809, 2023). "For the first time, mycobacteria from mice and melanoma patients were shown to play a pivotal role in immune stimulation of CTLA-4 blockade, with the antitumor effects of CTLA-4 blockade dependent on different mycobacterial species." (PMID 37190201, 2023). "The first drug to be developed against CTLA-4 was ipilimumab, a mAb capable of antagonizing CTLA-4, for its use alone or in combination, in the treatment of melanoma, prostate, breast, renal and other cancers." (PMID 38162657, 2023). "Co-inhibition of PD-1 and CTLA-4 has an antitumor effect in patients with OCCC, but with severe adverse events; however, a randomized phase III study on melanoma revealed that co-inhibition of PD-1 and LAG-3 leads to favorable outcomes." (PMID 37179337, 2023). "We show that domatinostat (a class I histone deacetylase inhibitor) addition to anti-PD-1 + anti-CTLA-4 increased the IFN-γ response and reduced tumor growth in our murine melanoma model, rationalizing evaluation in patients." (PMID 36920329, 2023). "In an experimental mouse model of melanoma that used a monoclonal antibody against MARCO, a scavenger receptor on TAMs reduced the presence of M2 TAMs and improved the effectiveness of anti-CTLA-4 antibody therapy." (PMID 38139110, 2023). "As one of the most extensively studied immune checkpoints, CTLA-4 has been the target of inhibitor development, with ipilimumab being the first to be approved by FDA in 2011, for attacking melanoma cells." (PMID 37576404, 2023).